ARG1 (arginase 1)
Diseases named in the same sentence as ARG1 in open-access papers (continued):
Sharing a sentence is not in itself a finding about the gene and the disease.
colon carcinoma (29 papers, 2015 to 2026). "Spatial metabolomics data indicated significant alterations in arginine metabolic pathways within the colon tumor model due to GDNPs, potentially linked to the reduction of ARG1 releasing during GDNPs-induced macrophage reprogramming." (PMID 38012650, 2023). "Colegio and colleagues further demonstrated that HIF-1α expression in tumor macrophages induce M2-associated genes such as VEGF, arginase 1 (Arg1), macrophage galactose-type lectin-1 (Mgl1) and macrophage galactose-type lectin-2 (Mgl2) in a colon carcinoma mouse model." (PMID 30619850, 2018). "Therefore, we speculated that the blockade of ARG1 associated with this malignant transformation might be a promising strategy for the treatment of colon cancer patients." (PMID 36639644, 2023). "In a colon cancer animal model, overexpression of decoy receptor 3 led to enhanced tumor growth in association with an increase in M2 phenotypic macrophages/dendritic cells, which was abolished by antagonism of arginase 1, an inducer and marker of M2 macrophages/dendritic cells." (PMID 26378024, 2015). "Increased expression of Arg-1 in colon tumor tissue significantly inhibited the secretion of IFN-γ and IL-2 by colon CD8+ T cells." (PMID 36713833, 2023). "In this study, we demonstrated that ARG1 activity is related to the metastatic colonization of colon cancer cells in the liver and lung tissue of mice." (PMID 36639644, 2023). "We further evaluated the effects of ARG1 overexpression on the malignant alteration of colon cancer cells." (PMID 36639644, 2023). "Overexpression of ARG1 in colon cancer cells reduced their intracellular l-arginine levels, enhancing their migration ability." (PMID 36639644, 2023). "The molecular mechanism of ARG1-mediated malignant alteration of colon cancer cells is poorly understood." (PMID 36639644, 2023). "To address the effects of ARG1 overexpression on amino acid metabolism in colon cancer cells, we conducted an analysis of the intracellular free amino acid levels for Arg1 OE compared with the mock control." (PMID 36639644, 2023). "A striking finding of our study was the increased infiltration of MDSCs and up-regulation of Arg-1 activity in colon tumor tissues, while WGP treatment significantly reduced the number and function of MDSCs." (PMID 36713833, 2023). "In this study, we revealed that Arg1 overexpression significantly promoted the metastatic colonization of colon cancer cells in tumor-bearing mouse models." (PMID 36639644, 2023). "Our data suggest that activation of ARG1 promotes the migration, colonization, and metastasis of colon cancer cells in tumor-bearing hosts." (PMID 36639644, 2023). "We established ARG1-overexpressing CT26 cells to evaluate the effects of ARG1-mediated arginine metabolism on the malignancy of colon cancer cells." (PMID 36639644, 2023). "They found that the levels of IL-10 and arginase-1 increased, indicating that the colon cancer cells were involved in the M2 polarization of THP-1, which was also confirmed by using the EGFR antibody mAb225 and the PI3K inhibitor LY294002." (PMID 36709284, 2023). "Related research showed that triptolide-educated colon cancers retarded the macrophages' polarization to anti-inflammatory M2 status by decreasing the expression of Arg-1 and CD206, the markers of M2 polarization." (PMID 35497923, 2022). "This was in contrast to the phenotype we previously observed in LysM-MK2-KO mice, where Arginase-1 positive cells were dramatically reduced in colon tumors, despite the total numbers of macrophages being similar." (PMID 33708191, 2020). "We next immunostained colon tumors for the broad macrophage marker F4/80 and the M2 specific marker Arginase-1 in the WT and LysM-MK2-KO mice following reconstitution with WT macrophages." (PMID 33708191, 2020). "Macrophages expressing high levels of both inducible nitric oxide synthase (M1 marker) and arginase-1 (M2 marker) have been described in mouse models of colon carcinoma and sarcoma." (PMID 27119077, 2016).
colon carcinoma (continued). "Treatment with conditioned medium of colon cancer cells increased macrophage expression of the M2-related markers arginase-1 (Arg1), CCL17, CCL22, IL-10 and IL-4." (PMID 27683110, 2016). "The association between ARG1 expression and survival was not restricted to a particular gender, except for colon cancer, where we only found an association in the male patients." (PMID 40474277, 2025). "Additionally, it has been reported that the metformin treatment decreased the ARG1 activity of granulocytic myeloid-derived suppressor cells in a tumor-bearing mouse model of colon carcinoma." (PMID 36982390, 2023). "From these data, we speculated that ARG1 overexpression of CT26 colon cancer cells in tumor tissues was possibly related to the augmentation of the serum arginase activity and metastatic colonization in the mouse model." (PMID 36639644, 2023). "Then, we evaluated the effects of ARG1 on the malignancy of human colon cancer cells." (PMID 36639644, 2023). "We established metastatic colonization mouse model and ARG1 overexpressing murine colon cancer CT26 cells to investigate whether activation of ARG1 was related to malignancy of colon cancer cells in vivo." (PMID 36639644, 2023). "We report here that ARG1 activation is involved in the metastatic colonization of colon cancer cells and its blockade may be a novel strategy for cancer malignancy." (PMID 36639644, 2023). "Activation of ARG1 is related to the migration ability and metastatic colonization of colon cancer cells, and blockade of this process may be a novel strategy for controlling cancer malignancy." (PMID 36639644, 2023). "The poor survival of colon cancer patients is related to a higher expression of ARG1." (PMID 33915902, 2021). "Moreover, colon cancer-derived insulin-like growth factor-1 (IGF-1) increased Arg1 expression, and treatment with the IGF1R inhibitor AG1024 inhibited that increase." (PMID 27683110, 2016). "Therefore, we speculated that ARG1 possibly promoted the migration ability and metastatic colonization of colon cancer cells through the augmentation of EMT pathways in this study." (PMID 36639644, 2023). "Furthermore, many researchers revealed that ARG1-expressing MDSCs induced in a tumor-bearing state were related to the tumorigenesis of colon cancers, and the blockade of this immunosuppressive function showed anti-tumor effects, indicating promising targets for the treatment of CRC patients." (PMID 36639644, 2023). "Therefore, our in vivo results indicate that not only does ARG1 activation augment the malignancy of colon cancer cells but also it modulates the tumor microenvironment involved in the dysfunction of host immunity, which facilitates the metastatic colonization of colon cancer cells in the liver." (PMID 36639644, 2023). "However, whether ARG1 activation is related to the progression and metastatic colonization of colon cancer cells remains unclear." (PMID 36639644, 2023). "However, it is unclear whether ARG1 controls the progression and malignant alterations of colon cancer." (PMID 36639644, 2023). "Elevated soluble Arg-1 levels were previously detected in HNSCC, breast, lung or colon cancer patients." (PMID 38001706, 2023). "As a consequence, TAMs and granulocytes release mediators such as arginase 1 (ARG1) and hematopoietic cell kinase (HCK) that impair T-cell responses and promote tumor invasion in lung and in colon cancers." (PMID 34084172, 2021). "Nevertheless, unexpectedly ARG1 expression did not exhibit negative prognostic relevance in colon cancer." (PMID 38557819, 2024). "Indeed, we find that treatment of MC38 colon tumors with 6-OAU inhibits the TAMs polarization toward pro-tumorigenic TAMs as evidenced by reduced CD206 and Arg1." (PMID 38349405, 2024). "ARG1 gene expression was higher in the tumor tissues of liver metastasis than those of primary tumor, and arginase inhibition suppressed the migration ability of HCT116 human colon cancer cells." (PMID 36639644, 2023).
colon carcinoma (continued). "The expression of M2-like macrophage markers Arg1, MRC1 and IL-10, CCL17, and CCL22 were down-regulated, and the expression of M1-like macrophage markers iNOS, IL-12, and TNFa were induced by cetuximab in modeled TAMs, treated with CM of colon cancer cells in vitro." (PMID 34209679, 2021).
Obesity (28 papers, 2016 to 2026). Accumulation of substantial excess body fat. "Chronic inflammation and metabolic abnormalities associated with obesity are thought to increase the activity of arginase 1, an enzyme that competes with nitric oxide (NO) synthase for arginine." (PMID 39458496, 2024). "Winer38 observed that diet-induced obesity led to a reduction in the expression of Ym1, arginase 1, and Il10 genes, causing a shift in the polarization state of macrophages from an anti-inflammatory M2 state to a proinflammatory M1 state in ATMs." (PMID 38263234, 2024). "Therefore, changes in arginase 1 expression in adipose tissue macrophages have an enormous impact on obesity-associated adipose tissue inflammation." (PMID 31622373, 2019). "Endothelial ARG1 exacerbates obesity-related vascular dysfunction, while keratinocyte ARG1 impacts wound healing and psoriasis." (PMID 41939876, 2026). "In HFD mice, upregulation of ARG1 reduces infiltration of macrophages in adipose tissue and facilitates polarization of macrophages to M2, thus alleviating obesity and improving insulin sensitivity." (PMID 36338341, 2022). "On the contrary, M2 macrophages protect against obesity-induced AT inflammation and IR by expressing higher levels of anti-inflammatory cytokines such as IL-10 and arginase-1 (Arg-1), which facilitate the maintenance of local immune and metabolic homeostasis." (PMID 36297306, 2022). "In epididymal white adipose tissue (eWAT), abnormal ARG1 expression induced by an imbalance of M1- and M2-macrophage proportions is able to provoke adipose tissue dysfunction and obesity-related IR." (PMID 36338341, 2022). "In high fat-high sucrose- (HFHS-) stimulated obesity mice, endothelial-specific ARG1 knockout attenuates obesity-induced adipose tissue inflammation via maintaining endothelial NO levels." (PMID 36338341, 2022). "Patients with type 2 diabetes are commonly associated with obesity, which induces the M2 phenotype of macrophages through the transactivation of arginase-1 that promotes hepatic glucose and lipid metabolic balance to reduce obesity." (PMID 33995278, 2021). "We further analyzed in eWAT the expression of Arg1, a hallmark of alternatively activated macrophages and Ccl5 given its role in local inflammation of visceral WAT in obesity." (PMID 33924880, 2021). "More importantly, our results demonstrated that PCB2 ameliorated obesity-related inflammation via a PPARγ-dependent up-regulation of Ym1, Arg1, and Fizz1." (PMID 31440258, 2019). "Next, we chose to look at how Arg1 mRNA was impacted in Sfrp1−/− mice fed a high fat diet (HFD) and our findings reveal that the expression of the Arg1 is also significantly elevated in response to diet-induced obesity (DIO) in the mammary gland of Sfrp1−/− mice." (PMID 38554160, 2024). "We measured a murine M2 marker (Arg1) in mice with a targeted deletion of Sfrp1 during different stages of mammary gland development including puberty, pregnancy, and lactation, as well as in response to obesity." (PMID 38554160, 2024). "CD163, CD206, and arginase-1 (Arg-1) act as makers of an alternative activation of monocytes/macrophages (M2, anti-inflammatory phenotype), and play a crucial role in chronic inflammation of obesity-related metabolic diseases." (PMID 36687421, 2022). "Transactivation of macrophage ARG1 drives an anti-inflammatory M2 phenotype, which lowers inflammation, promotes white adipose tissue (WAT) beiging, and maintains metabolic homeostasis in WAT, thereby reducing the risk of obesity-related DM." (PMID 36338341, 2022). "Diet-induced obesity did not alter expression of Tnfa, Nos2, Il12, Il10, but was associated with a significant increase in Retnla expression and a small reduction in Il6, and Arg1 expression." (PMID 26956558, 2016).
Obesity (continued). "Mechanistically, an imbalance in M1 and M2 macrophage proportions in WAT promoted iNOS (inducible nitric oxide synthase): arginase-1 imbalance that resulted in extracellular matrix (ECM) deposition and insulin resistance development and consequently obesity." (PMID 35578225, 2022). "In a model of diet-induced obesity (DIO), Ron−/− mice exhibit exacerbated CNS inflammation with decreased expression of the M2 marker Arginase-1 (Arg-1) and a robust increase in M1 markers compared to WT mice following 27 weeks of DIO." (PMID 29616029, 2018). "Additionally, exosomes from adipose-derived stem cells (ADSCs) facilitate immune and metabolic homeostasis in WAT through the transactivation of ARG1 by exosome-carried active STAT3, thereby relieving obesity-related IR." (PMID 36338341, 2022). "In comparison, hAMSCs-CM effectively reversed HFD-induced decreases of ARG-1 and increase of the phosphorylated STAT3, suggesting that the anti-obesity of hAMSCs-CM might be involved in their anti-inflammation." (PMID 34174964, 2021). "There is an effect of obesity status but not diet on liver ARG-1, MPO, and SREBP-1 expression." (PMID 38075211, 2023). "In addition, another study demonstrated that treatment ofmacrophages with 5-AZAdC increased ARG1 expression in these cells, and increased the population of F4/80+CD206+ M2 macrophages and reduced TNF-α production, controlling inflammation response in obesity." (PMID 33921194, 2021).
ischemic stroke (27 papers, 2016 to 2026). A stroke disorder caused by obstruction of blood flow to the brain, due to thrombotic (local blood clot formation) or embolic (due to a blood clot or other material traveling from another site) event. "Further, neuronal survival was associated with the number of arginase-1 positive microglia in a murine model of ischemic stroke." (PMID 34214084, 2021). "Furthermore, increased expression of ARG1 in microglia following ischemic stroke is linked to improved tissue remodeling and behavioral recovery (Asano, Chantler & Barr, 2016)." (PMID 27672514, 2016). "On the other hand, ADAMTS4 seems to decrease inflammation after ischemic stroke by increasing the number of microglia expressing arginase-1, a marker of alternatively activated cells with anti-inflammatory functions." (PMID 37378751, 2024). "We found ischemic stroke enhanced MG Arg1 and CD206 expression in the ipsilateral hemisphere of vehicle-treated MCAO mice compared to that of sham controls at day 2 post-injury." (PMID 37063896, 2023). "A recent study using a mouse model of cortical photothrombotic ischemic stroke, found more severe ischemic injury exacerbated neuronal damage and an increased the inflammatory response in animals in which Arg1+ microglia/macrophages were depleted." (PMID 37208759, 2023). "Growing evidence indicates that ischemic stroke also induces upregulated Arg1 expression in the central nervous system, especially in activated microglia and macrophages." (PMID 36361836, 2022). "We have recently shown that treatment with a stable, pegylated drug form of the ureohydrolase enzyme arginase 1 (A1) provides neuroprotection in acute models of ischemia/reperfusion injury, optic nerve crush, and ischemic stroke." (PMID 36038541, 2022). "To evaluate the effect of Arg1+ microglia/macrophages depletion on ischemic damage, we first assessed the behavioral performance after ischemic stroke." (PMID 36361836, 2022). "It demonstrates that Arg1+ microglia/macrophages play an important role in regulating the immune microenvironment of the brain, acting as a neuroprotective agent in ischemic stroke." (PMID 36361836, 2022). "To investigate the dynamic response of Arg1+ cells, we measured cell densities within the first week after ischemic stroke." (PMID 36361836, 2022). "The functional implication of Arg1 is twofold: first, by competing with iNOS for substrates, Arg1 has potent anti-inflammatory effect; second, Arg1 was previously reported to enhance phagocytic function of Mi/MΦ after ischemic stroke." (PMID 37516843, 2023). "The Arg1+ microglia/macrophages alleviate ischemic injury by releasing anti-inflammatory factors and inhibiting the production of pro-inflammatory factors, thereby influencing the pathological development of ischemic stroke." (PMID 36361836, 2022). "Our group has recently demonstrated that Arg1 has a neuroprotective role in mouse models of both retinal ischemia/reperfusion injury and ischemic stroke, and further demonstrated the beneficial effects of Arg1 treatment in the form of intravitreal and intraperitoneal injections." (PMID 36139465, 2022). "Furthermore, it has been shown that activated neutrophils following ischemic stroke are a major source of Arg-1 that leads to T-cell dysfunction and immunosuppression." (PMID 34149350, 2021). "Therefore, the Arg1+ microglia/macrophages can be considered as a target subpopulation that could be regulated in ischemic stroke." (PMID 36361836, 2022). "Although the simple dichotomy of microglia/macrophages is controversial, a part of microglia/macrophages are indeed found to upregulate Arg1 expression after cerebral ischemia, and they may act together as a whole to influence the progression of ischemic stroke." (PMID 36361836, 2022).
ischemic stroke (continued). "In the present study, our findings revealed that IFNβ attenuated tPA-upregulated inflammatory molecules, CD86, IL-1α, and IL-1β, and promoted anti-inflammatory molecules, Arg1 and CD206, in MG during the acute phase of ischemic stroke." (PMID 37063896, 2023). "The phagocytosis effects of other molecules, such as Arg-1 and PPAR γ, were also reported in ischemic strokes." (PMID 35237132, 2022). "To further analyze the phenotype of recruited microglia and macrophages within the ischemic stroke lesion, as well as the effect of IL13-MSC thereon, we first performed additional immunofluorescence staining for Arg-1." (PMID 29866203, 2018). "To detect whether ADSC-EVs could regulate the polarization of microglia after ischemic stroke, we performed CD16/Iba1 and Arg-1/Iba1 double-staining to detect M1 phenotype and M2 phenotype microglia, respectively." (PMID 35057862, 2022). "Additionally, mRNA samples in the present study were all from PBMCs, thus we suggest that ARG1 and MMP9 could be used as biomarkers for the detection of ischemic stroke." (PMID 27672514, 2016). "A study on the mechanism of signal transducer and activator of transcription 6/arginase 1 (STAT6/Arg1) in ischemic stroke found that microglia not only phagocyte a large number of apoptotic neurons, but also a small number of viable neurons after ischemic stroke." (PMID 33650762, 2021).